IL10 (interleukin 10)
Diseases named in the same sentence as IL10 in open-access papers (continued):
Sharing a sentence is not in itself a finding about the gene and the disease.
hyperuricemia (4 papers, 2020 to 2023). An abnormally high level of uric acid. "Patients receiving CAR T-cell therapy can develop fulminant HLH and present with increased lactate dehydrogenase, hyperuricemia, IL-10, IL-6, and IFN-γ." (PMID 37010812, 2023). "Hyperuricemia induced a state of inflammation and significantly increased IL-1β and TNF-α levels (P < 0.05), while decreasing serum levels of IL-10." (PMID 32528050, 2020).
hypoxic-ischemic encephalopathy (4 papers, 2015 to 2024). "Studies have shown that elevated levels of IL-6, IL-10, and TNF-α in cerebrospinal fluid (CSF) may be associated with brain injury in both neonatal hypoxic-ischemic encephalopathy (HIE) and preterm infants with MRI-defined brain white matter injury." (PMID 38494527, 2024). "However, the mechanism by which Chinese Tuina improved the inflammatory response in neonatal hypoxic-ischemic encephalopathy was independent of the regulation of methylation levels in IL-10 and TNF-α." (PMID 33488693, 2020).
IgA nephropathy (4 papers, 2015 to 2022). "Tonsillar mononuclear cells of patients with IgA nephropathy exhibited a higher capability to produce transforming growth factor-β and interleukin-10 along with total IgA after stimulation with OMHP antigens than those from patients with chronic tonsillitis in vitro." (PMID 26078982, 2015).
ileus (4 papers, 2018 to 2023). Decrease in peristalsis in the absence of a mechanical bowel obstruction. "In line with this, an in vitro study showed that IL-10 was linked to disturbed motility in postoperative ileus, indicating that this anti-inflammatory cytokine has the potential to facilitate peristaltic disturbances." (PMID 37189645, 2023). "In a gut manipulation model of ileus in mice (C57BL/6), IL-10 deficiency attenuated the development of ileus." (PMID 35805922, 2022). "No statistical difference was observed between pressures or the existence of an ileus, but the maximum levels of IL‐6 and IL‐10 detected in some patients reflect a pressure difference." (PMID 37636200, 2023). "In rats with postoperative ileus, expression of TNF-α, IL-1β, IL-6, and IL-10 is reduced by Rb1 in ileum tissue, along with gastrointestinal transit increased, indicating a potent anti-inflammatory effect." (PMID 30402203, 2018). "In a rat with postoperative ileus, ginsenoside Rb1 reduces serum concentration of TNF-α, IL-1β, IL-6, and IL-10, indicating its anti-inflammatory effect." (PMID 30402203, 2018).
imbalance (4 papers, 2023 to 2025). "This study demonstrates that maternal immune imbalance in late pregnancy—particularly an elevated IL-6/IL-10 ratio—acts as a biologically relevant determinant of fetal telomere shortening, independent of common clinical risk factors." (PMID 40868226, 2025).
immunosuppressive (4 papers, 2014 to 2025). "Immunosuppression is also associated with changes in related cytokines released by lymphocytes, such as decreases in interferon-gamma (INF-γ) and interleukin-10 (IL-10)." (PMID 34149601, 2021). "It is also well known that PRRSV is an immunosuppressive disease, and IL-10 is a vital immunosuppressive factor during PRRSV infection." (PMID 30353051, 2018). "While in VL IL-10 is considered to be the marker of the severe immunosuppressive disease, IL-10 in human CL has been shown to be related to the pathology of the disease as well as the control of the parasite." (PMID 24966857, 2014).
IPEX syndrome (4 papers, 2011 to 2022). "The relevance of other peripheral tolerance mechanisms, such as the presence and function of type 1 regulatory T (Tr1) cells, the major adaptive IL-10-producing Treg subset, in patients with IPEX syndrome remains to be clarified." (PMID 21400500, 2011). "We further investigated the presence of circulating IL-10-producing cells in the peripheral blood of patients with IPEX syndrome by evaluation of IL-10 production by patients' PBMCs upon TCR-mediated stimulation." (PMID 21400500, 2011). "Finally, in other circumstances, curative interventions are enabled in otherwise life-threatening disease, such as BMT for IL10 signaling defects, CGD, IPEX syndrome and OS, and sets the groundwork for investigating gene therapy and manipulation of the microbiome." (PMID 36248828, 2022).
ischemia reperfusion injury (4 papers, 2014 to 2024). Adverse functional, metabolic, or structural changes in ischemic tissues resulting from the restoration of blood flow to the tissue (reperfusion), including swelling; hemorrhage; necrosis; and damage from free radicals. "While the treatment of CXCR3-deficient mice with concanavalin A results in a decreased recruitment of IL10-producing CXCR3+ Tregs, CXCR3 blockade in a model for ischemia-reperfusion injury causes a reduction in intrahepatic Th1 cells." (PMID 24646914, 2014). "In a pre-clinical model of ischemia-reperfusion injury, prazosin administration resulted in decreased expression of IL-6, TNF-α, IL-10, and IL-1, and prevented mortality." (PMID 33869251, 2021). "Moreover, IL-10 signaling is protective in different models of AKI, including cisplatin-induced nephrotoxicity, ischemia-reperfusion injury (IRI), and endotoxin-induced AKI." (PMID 39621679, 2024).
kidney injury (4 papers, 2020 to 2023). Trauma to the kidney. "In our study, the IL-10 level remained at a high level in the 10th day, which may be because the mice were still injected with glyoxylate which caused acute kidney injury at this time." (PMID 33204326, 2020).
lactic acidosis (4 papers, 2013 to 2024). Metabolic acidosis characterized by the accumulation of lactate in the body. "Pro-inflammatory responses to hyperchloremic metabolic acidosis are mediated by nitric oxide and are associated with a higher interleukin (IL)-6 to IL-10 ratio when compared with lactic acidosis, as reported in in vitro cell models." (PMID 27716363, 2016).
macular edema (4 papers, 2012 to 2023). "Aqueous level of VEGF has been shown to correlate positively with macular thickness and severity of macular edema, whereas aqueous IL-10 level correlates inversely with severity of macular edema." (PMID 28558009, 2017). "In addition, the aqueous humor levels of IL-10 and IL-12 were significantly lower in diabetic patients with macular edema, and the concentrations of these two cytokines decreased with increasing severity of macular edema." (PMID 25923230, 2015). "In addition, the aqueous humor levels of IL-10 and IL-12 decreased with increasing severity of macular edema, and this negative correlation was significant." (PMID 25923230, 2015).
meningoencephalitis (4 papers, 2015 to 2022). Inflammation of the meninges and brain, generally secondary to an infectious cause. "On the other hand, TNF-α/IL-10 and IL-17/IL-10 ratios were significantly lower in virus positive when compared to undiagnosed meningoencephalitis patients." (PMID 26286516, 2015). "In the present research, we described histopathological changes, viral dissemination, glial reaction, and expression of TNFα, TGF-β, INF-γ, IL-6, IL-10, IL-12p40, IL-12p70, MCP-1, and NO in the brains of young adult mice after Maraba virus-induced meningoencephalitis." (PMID 32294697, 2020). "The diads IL-10/IFN-γ and IL-6/IL-17 are present only in undiagnosed meningoencephalitis patients regardless of cellularity." (PMID 26286516, 2015). "The levels of IL-6, IL-10, IFN-α and IFN-γ were significantly higher in the CSF samples from patients suffering of viral meningitis or meningoencephalitis as compared to noninfectious CNS diseases." (PMID 26569288, 2015). "In this regard, several ratios between cytokines were altered such as IFN-γ/IL-10, IFN-γ/TNF-α and IFN-γ/IL-17 (data not shown) in patients with meningoencephalitis." (PMID 26286516, 2015).
monocytic leukemia (4 papers, 2016 to 2025). "The frequencies of CD86+ and CD163+ cells and expression levels of these markers as well as the cytokines IL-12 and IL-10 were measured in THP-1- (human monocytic leukemia cell) derived macrophages." (PMID 30276219, 2018). "On the other hand, magnetic nanoparticles induced formation of membranous ferroportin and incited secretion of ferritin, TNF-α, and IL-10 in human histiocytic lymphoma cells (U937) and human monocyte leukemia cells without any decrease of cell viability." (PMID 27106358, 2016).
oropharyngeal carcinoma (4 papers, 2015 to 2019). Carcinoma, predominantly squamous cell, arising from the epithelial cells of the oropharynx. "Our previous study is in agreement with these findings as increased level of different cytokines, including IL-10, was stated in patients with oropharyngeal cancer infected with EBV, indicating IL-10 involvement in the process of cancer development." (PMID 31360295, 2019). "The aim of this study was the analysis of the serum and salivary levels of IL-10, TNF-α, TGF-β and VEGF in patients with oropharyngeal cancer and in healthy individuals." (PMID 27547238, 2016). "Therefore, the aim of this study was to analyze the serum and salivary levels of IL-10, TNF-α, TGF-β and VEGF in patients with oropharyngeal cancer compared to healthy individuals." (PMID 27547238, 2016).
pancolitis (4 papers, 2016 to 2023). Ulcerative colitis that involves the entire colon. "In addition, studies show IL-10 and IL-10R1 levels were increased in transverse colon biopsies of patients with extensive/pancolitis, compared with control subjects and patients with limited distal disease." (PMID 37457023, 2023). "After 4 weeks of colonization, IL-10−/− mice showed mild pancolitis independent of the colonizing bacteria." (PMID 31281321, 2019).
pancreatic adenocarcinoma (4 papers, 2014 to 2024). "IL10 correlates with increased risk in KIRP and pancreatic adenocarcinoma (PAAD), yet displays protective tendencies in LUSC, emphasizing its variable role across different tumor microenvironments." (PMID 39635438, 2024). "Our analysis demonstrated that IL-6, IL-8, IL-10, and TNFα are promising novel candidate markers for the detection of pancreatic adenocarcinoma, whereas IL-23 might be valuable for its ability to exclude a diagnosis of cancer." (PMID 24849506, 2014). "In fact, IL-10 acts as a mediator of the anti-inflammatory response and as an inhibitor of macrophages and dendritic cells (DCs), and TGF-β is known to act as a pro-tumorigenic by induction of an epithelial-mesenchymal transition (EMT) in pancreatic adenocarcinoma." (PMID 31936786, 2020). "The SEQUOIA study aimed to assess whether adding pegilodecakin (a type of interleukin-10 that has been modified to stay in the body longer) to FOLFOX (a chemotherapy regimen) as a second-line treatment would be effective in patients with pancreatic adenocarcinoma who did not respond to gemcitabine." (PMID 37366887, 2023).
pancreatic ductal adenocarcinoma (4 papers, 2017 to 2022). An infiltrating adenocarcinoma that arises from the epithelial cells of the pancreas. "Monocytes co-cultured with CAFs from pancreatic ductal adenocarcinoma have been shown to present with increased surface expression of specific M2-markers, e.g., CD163, CD200R, and CD206 surface receptors and up-regulation of ARG1, IL10, and TGFB1 genes." (PMID 31108906, 2019).
Peripheral T-Cell Lymphomas (4 papers, 2017 to 2024). "Among peripheral T-cell lymphomas ALCL has been associated with the highest level of IL-10 expression, and ALCL cells also express the IL-10 receptor, which provides an autocrine mechanism for the aberrant activation of TYK2 in ALCL cells." (PMID 30131584, 2019).
pituitary adenomas (4 papers, 2019 to 2025). "The aim and objective of this study is to determine the association between the rs1800871, rs1800872, and rs1800896 polymorphisms of the gene IL-10 and the serum levels of IL-10 in patients with pituitary adenoma." (PMID 36009467, 2022). "Therefore, this study aims to investigate the polymorphisms of the IL-10 gene, rs1800871, rs1800872, and rs1800896, and IL-10 serum levels in association with pituitary adenomas." (PMID 36009467, 2022). "Therefore, supported by our results, we speculate that in pituitary adenoma, SRLs may inhibit macrophage activation through increased IL‐10." (PMID 40789673, 2025).
Pneumocystis infection (4 papers, 2010 to 2021). "In addition, CD28-deficient mice have an increase in IL-10 levels, which is notable since IL-10-deficient mice have improved clearance of Pneumocystis infection." (PMID 33669726, 2021). "During Pneumocystis infection, IL-10 was demonstrated to play a protective role in reducing the immune response to pathogen, alleviating lung damage, and mediating B cell protection-demand hematopoiesis in PCP hosts." (PMID 31582901, 2019). "RT-PCR data demonstrated that IL-17 and STAT3 gene expression was significantly increased in the lung from IL-10–/– PCP mice than that from WT PCP mice at 2 wk after Pneumocystis infection." (PMID 31582901, 2019). "During Pneumocystis infection, IL-10 downregulates the immune response to pathogen in WT mice and plays an important role in controlling lung damage." (PMID 31582901, 2019). "IL-17 and IL-10 could both play protective roles in Pneumocystis infection via attenuating lung damage and assisting the clearance of pathogen." (PMID 31582901, 2019). "The expression of IL-10 was not affected by dexamethasone treatment but was up-regulated 1.87 fold by Pneumocystis infection." (PMID 20377877, 2010).
pneumocystis pneumonia (4 papers, 2016 to 2022). "Our present study focused on the immune regulatory roles of IL-17 and IL-10 in Pneumocystis pneumonia." (PMID 31582901, 2019).
primary effusion lymphoma (4 papers, 2022 to 2025). A large B-cell lymphoma located in the body cavities, characterized by pleural, peritoneal, and pericardial fluid lymphomatous effusions and that is always associated with human herpes virus-8 (HHV-8). "Moreover, quercetin inhibited IL-6 and IL-10 cytokine production, resulting in the cytotoxicity of primary effusion lymphoma (PEL)." (PMID 40427522, 2025).
pterygium (4 papers, 2021 to 2024). A wedge-shaped fibrovascular lesion arising from the bulbar conjunctiva and extending to the cornea. "Additionally, IL-10’s tissue repair-promoting effects could support healing after pterygium surgery and reduce the risk of recurrence." (PMID 39682531, 2024). "The higher levels of IL-10 in primary pterygium compared to recurrent pterygium indicate an enhanced early protective response aimed at limiting pterygium progression and controlling the inflammatory process." (PMID 39682531, 2024). "In the primary pterygium group, only IL-10 was significantly higher compared to the recurrent pterygium group (p = 0.0054)." (PMID 39682531, 2024). "The elevated IL-10 levels observed in primary pterygium compared to recurrent pterygium may indicate an enhanced early protective response aimed at limiting pterygium progression and controlling inflammation." (PMID 39682531, 2024). "Given the role of TGF-β1 in fibrotic processes and the suppressive effect of IL-10 on inflammation, the changes in the expression of these genes may be crucial in the pathophysiology of recurrent pterygium." (PMID 39682531, 2024). "In patients developing pterygium for the first time, IL-10 production may be increased as an early protective response to limit pterygium progression and control the inflammatory process." (PMID 39682531, 2024). "In this microenvironment, increased IL-10 production may suppress inflammation and slow the progression of pterygium." (PMID 39682531, 2024). "Given IL-10’s role in pterygium pathophysiology as an anti-inflammatory agent, targeting IL-10 with a specific drug could be a promising strategy for preventing recurrence." (PMID 39682531, 2024). "The anti-inflammatory properties of IL-10 may suppress the inflammatory processes of pterygium and prevent its recurrence." (PMID 39682531, 2024). "Furthermore, IL-10’s ability to induce immune tolerance may be crucial in preventing pterygium recurrence." (PMID 39682531, 2024). "Therefore, a drug that regulates IL-10 levels could help balance immune responses in the pathogenesis of pterygium." (PMID 39682531, 2024). "The findings obtained in our study suggest that TGF-β1 and IL-10 play critical roles in recurrent pterygium, while other inflammatory cytokines do not contribute significantly, at least statistically." (PMID 39682531, 2024). "The downregulation of IL-10 suggests that inflammatory processes may not be adequately suppressed in recurrent pterygium, pointing to the potential importance of inflammation in the recurrence of this condition." (PMID 39682531, 2024). "The dichloromethane extract of S. dendroideum promoted corneal healing in a murine model of pterygium-like eye lesions and exhibited immunomodulatory effects by reducing the levels of pro-inflammatory cytokines TNF-α and IL-1α, maintaining the expression of the anti-inflammatory cytokine IL-10." (PMID 37895904, 2023).
Pulmonary hemorrhage (4 papers, 2016 to 2025). Pulmonary hemorrhage is a bleeding within the lungs. "Patients with severe pulmonary haemorrhage had significantly higher levels of IL-5, IL-6, IL-8, and IL-10." (PMID 32264832, 2020).
pulpitis (4 papers, 2021 to 2024). Inflammation of the dental pulp. "Pulpitis is characterized by the production of high levels of pro-inflammatory cytokines including TNFα, IL-4, IL-6, IL-8, IL-10 and CXCL8." (PMID 35902880, 2022). "Treg as a subset of T lymphocytes has been playing a pivotal role in the immune and inflammatory response of pulpitis by secreting anti-inflammatory cytokines, including interleukin-10 and transforming growth factor b (TGF-b)." (PMID 33777260, 2021). "IL-10 acts as an anti-inflammatory cytokine that may be protective in terms of pulpitis development, decreasing IL-6 release, inhibiting Th1 and Th2 immune response, and thus, limits the intensity of inflammatory reaction." (PMID 33801317, 2021). "In addition to improving the environment for the regeneration of pulp tissue, DPSC-Exos have also been elucidated to alleviate dental pulp inflammation by transferring higher levels of anti-inflammatory factors, such as TGF-β and interleukin-10 (IL-10)." (PMID 38540750, 2024).
respiratory distress syndrome (4 papers, 2017 to 2025). "However, elevated IL-10 levels in cord blood have been observed in preterm births and are associated with an increased risk of respiratory distress syndrome (RDS), highlighting the complex interplay between inflammatory regulation and disease pathogenesis." (PMID 40941746, 2025). "Even in the mixed group of term and preterm patients, IL-10 in cord blood was predictive for respiratory distress syndrome." (PMID 39529072, 2024).
rubella (4 papers, 2011 to 2023). A viral infection caused by the rubella virus. "Among vaccine responders, rubella vaccination induces a marked increase in IL-4 and IL-10 levels." (PMID 35075197, 2022). "That the levels of T cells and activated T cells (CD27+ and CD25+CD127+) can negatively influence the level of the emerging IgA response to rubella is also not surprising, as is the negative impact of IL-10, IFN-γ and the level of initially activated helpers (CD3+CD8−CD38+)." (PMID 36851738, 2023).
Schistosoma haematobium infection (4 papers, 2010 to 2023). "The study explored the association between single nucleotide polymorphisms (SNPs) in interleukin-10 (IL-10) and tumour necrosis factor alpha (TNF-α) promoter regions and susceptibility to Schistosoma haematobium infection." (PMID 34485462, 2020). "For instance, Gabonese children with urinary schistosomiasis have been shown to have a lower prevalence of a positive skin reaction to house-dust mite than those without the disease, a finding that was associated to IL-10 production." (PMID 21631925, 2011).